GJB2 (gap junction protein beta 2)
Diseases named in the same sentence as GJB2 in open-access papers (continued):
Sharing a sentence is not in itself a finding about the gene and the disease.
tumor (continued). "Overall, our findings demonstrated that GJB2 was an independent prognostic factor for manifold cancers Furthermore, GJB2 expression correlated with TMB, MSI, ICP, neoantigens, and tumor infiltration of immune cells in diverse cancer types." (PMID 37427102, 2023). "Therefore, GJB2 may play a key role in the tumor-immune interactions." (PMID 37427102, 2023). "The expression of CDK1, ECT2, GJB2, GPR37, GPX2, and GPX8 gene was up-regulated in the tumor group (p < 0.001), whereas the expression of TLR4 was down-regulated in the tumor group (p < 0.001) when compared with those in the normal group." (PMID 37689745, 2023). "Therefore, GJB2 could be a promising target for tumor therapy." (PMID 37427102, 2023). "In view of miRNA functional mechanism and oncogenic roles of GJB2, S100A2 and SPOCK2, upstream miRNAs of the three genes should be tumor suppressive miRNAs." (PMID 31794425, 2019). "In addition, GJB2 was found overexpressed in CD74- and CLTC-ROS1+ tumor specimens and cell lines, which positively correlates with patients presenting a poor prognosis." (PMID 39737401, 2024). "GJB2 is highly enriched in HCC malignant cells based on scRNA‐seq and promotes HCC progression by activating glycolysis through cytoplasmic translocation, which generates a suppressive tumor microenvironment." (PMID 39162005, 2024). "We characterized GJB2 and SCN9A expression in GBM tumor regions and subtypes." (PMID 38177502, 2024). "CDK1, ECT2, EZH2, GJB2, GPR37, GPX2, and GPX8 mRNA expression was up-regulated in the tumor group (p < 0.001), whereas GPX3, HYAL1, and TLR4 mRNA expression was down-regulated in the tumor group (p < 0.001) compared with those in the normal group." (PMID 37689745, 2023). "Overexpression of GJB2 has been identified to promote tumor growth, migration, and invasion via the PI3K/Akt pathway, and knockdown of GJB2 could reduce migration and invasion." (PMID 35936685, 2022). "Moreover, GJB2 expression levels showed significant negative correlation with the tumor infiltration levels of B cells in several tumors, especially CHOL." (PMID 37427102, 2023). "Therefore, we performed a comprehensive pan-cancer analysis of GJB2 expression levels in the tumor tissues and the adjacent normal tissues." (PMID 37427102, 2023). "However, we did not provide direct evidence for the role of GJB2 in tumor immune infiltration and its relationship with prognosis." (PMID 37427102, 2023). "According to the clinicopathological features, GJB2 overexpression was positively correlated with microvascular invasion, blood vessel invasion, and macrovascular invasion, whereas it was not significantly correlated with age, gender, tumor size, and TNM classification." (PMID 39162005, 2024).
cancer (56 papers, 2006 to 2025). A tumor composed of atypical neoplastic, often pleomorphic cells that invade other tissues. "The genetic susceptibility literature suggests that individuals with GJB2 or mitochondrial mutations are more vulnerable to environmental and pharmacological insults, which aligns with findings in cancer survivors exposed to cisplatin." (PMID 41463124, 2025). "EPIC database analysis showed positive correlation between GJB2 expression levels and the infiltration levels of cancer-associated fibroblasts (CAFs) in multiple tumors, especially OV and BRCA." (PMID 37427102, 2023). "Considering that fibrosis in cancer tissue is associated with poor prognosis, GJB2-positive CAFs are a promising target." (PMID 37648762, 2023). "Our study illustrates one mechanism by which GJB2 exerts its cancer-specific relevant effects, that is, causing changes in intercellular communication through the SPP1 signaling pathway." (PMID 37188183, 2023). "First of all, we evaluated GJB2 expression in different types of tumors by the TIMER database and concluded that the high expression of GJB2 was associated with a variety of cancers, and LUAD is one of the affected tumors." (PMID 37188183, 2023). "The specific GJB2 gene mutations including mutation types, mutation sites, and the corresponding number of cases were listed for all the cancer types." (PMID 37427102, 2023). "Third, we concluded that GJB2 expression was strongly associated with immune cell infiltration and prognosis of human cancers." (PMID 37427102, 2023). "Overexpression of GJB2 is associated with a poor prognosis in several human cancers." (PMID 39799398, 2025). "While these results provided limited support for the current pathogenic classification, we anticipate that as the All of Us Research Program reaches 1 million participants, we will be powered to clarify the association of these rare pathogenic mutations in GJB2 to cancer predisposition." (PMID 39799398, 2025). "We used the cBioPortal database to analyze mutations in the GJB2 gene in pan-cancer datasets." (PMID 37427102, 2023). "Furthermore, our data showed positive correlation between GJB2 expression levels and the infiltration status of multiple types of immune cells such as cancer associated fibroblasts (CAF), macrophages, myeloid dendritic cells, DCs, neutrophils, monocytes, and endothelial cells in most tumors." (PMID 37427102, 2023). "The biggest innovation of this study is that the localization of GJB2 in HCC cancer cells is changed compared to normal liver tissue." (PMID 39162005, 2024). "In summary, the localization of GJB2 in HCC cancer cells has changed compared with that in normal liver tissues." (PMID 39162005, 2024). "These compelling findings underscore GJB2's candidacy as a promising therapeutic target in the realm of cancer research." (PMID 39162005, 2024). "In cancer cells, GJB2 tends to be located in the cytoplasm and nucleus, while in normal liver cells, GJB2 is mainly located on the cell membrane." (PMID 39162005, 2024). "To validate the scRNA‐seq results, we used TCGA data to further predict the expression of GJB2 in HCC cancer and paracancer tissues, and the results showed GJB2 mRNA was lower expressed in cancer tissues (n = 371) compared with normal tissues(n = 50)." (PMID 39162005, 2024). "We used western blot to detect the expression of GJB2 in the cell membrane, cytoplasm, and overall in the paired tissues of cancer and adjacent tissues of 12 HCC patients with advanced stage, respectively." (PMID 39162005, 2024). "We were pleased to find that GJB2 in cancer tissue was more localized in cytoplasm and nucleus, while GJB2 in paracancerous tissue was more localized in cell membrane, which aroused our great interest." (PMID 39162005, 2024).
cancer (continued). "In order to further explore the changes of GJB2 transmembrane region, we used fluorescence immunohistochemical to detect the expression and localization of GJB2 protein in cancer tissue and paracancerous tissue samples from two HCC patients." (PMID 39162005, 2024). "It is interesting that the localization of GJB2 in HCC cancer cells was changed compared with normal liver tissue." (PMID 39162005, 2024). "Their findings revealed that a wide spectrum of cancers exhibited elevated expression levels of the GJB2 gene." (PMID 39162005, 2024). "Inhibition of GJB2 can not only kill cancer cells, but also reshape the microenvironment, which is conducive to the treatment of PD1 monoclonal antibody in HCC." (PMID 39162005, 2024). "In cancer cells, GJB2 tends to be located in the cytoplasm and nucleus, while in normal tissues, GJB2 is mainly located on the cell membrane." (PMID 39162005, 2024). "The results showed that the expression of total GJB2 protein in cancer tissues was higher than that in adjacent tissues, while the expression of GJB2 protein on the cell membrane was lower than that in adjacent tissues." (PMID 39162005, 2024). "In cancer cells, GJB2 tends to be located in cytoplasm and nucleus, while in normal tissues, it is mainly located in the cell membrane." (PMID 39162005, 2024). "The cBioPortal database was used to determine the characteristics of GJB2 gene alterations in the cancer tissues." (PMID 37427102, 2023). "In conclusion, these data demonstrated that GJB2 was a potential prognostic biomarker in multiple types of cancer." (PMID 37427102, 2023). "First, analysis of clinical data in the TIMER, GEPIA, and Sangerbox databases showed that GJB2 was highly expressed in 14 cancer types, including BRCA, CESC, LUAD, and STAD." (PMID 37427102, 2023). "In majority of the human cancer types, GJB2 showed positive correlation with immune scores, stromal scores, and ESTIMATE scores for the TME." (PMID 37427102, 2023). "In all patients with available clinical information (n = 8443), the GJB2 signature score was elevated in advanced-stage cancers." (PMID 37648762, 2023). "Our data provides the basis for exploring the clinical applications of GJB2-targeted cancer immunotherapy in the future preclinical and clinical studies as well as further exploring the biological role of GJB2." (PMID 37427102, 2023). "This study identifies a unique subgroup of terminally differentiated CAFs with high GJB2 expression and demonstrated their association with ECM remodeling, their interactions with endothelial cells, and their clinical significance in cancer progression." (PMID 37648762, 2023). "GEPIA and Kaplan–Meier plotter databases were used to analyze the survival outcomes based on GJB2 expression levels in pan-cancer." (PMID 37427102, 2023). "We then assessed the prognostic value of GJB2 in pan-cancer using the Kaplan–Meier plotter database." (PMID 37427102, 2023). "We also analyzed the correlation between GJB2 expression levels and clinicopathological parameters of cancer such as clinical stages, grades, gender, and age using the Sangerbox database." (PMID 37427102, 2023). "Relevant functional analyses revealed a role for GJB2 in extracellular matrix remodeling and activation of cancer-related signaling pathways." (PMID 37188183, 2023). "In most cancers, GJB2 expression levels showed positive correlation with the stromal scores and the immune scores." (PMID 37427102, 2023). "We demonstrated that GJB2-positive CAFs are a unique fibroblast subset, specialized for ECM remodeling and cancer-associated fibrosis." (PMID 37648762, 2023). "GSEA and KEGG functional analyses suggested high GJB2 expression was closely correlated with several cancer-related signaling pathways." (PMID 37188183, 2023). "The expression patterns of GJB2 in various cancer and normal tissues showed that it is mainly expressed specifically in CAFs and is poorly expressed in normal tissues." (PMID 37648762, 2023).
cancer (continued). "GJB2-positive fibroblasts are rarely found in normal tissues, but their predominance in cancer tissues suggests their lineage specificity for cancer-associated fibrosis." (PMID 37648762, 2023). "All these observations suggested that the anti-cancer effect triggered by quercitrin in LUAD is attributed to the inhibition of GJB2." (PMID 35196203, 2022). "We finally investigated the relationship between GJB2 and drug sensitivity based on the Genomics of Drug Sensitivity in Cancer (GDSC)." (PMID 35936685, 2022). "SLC25A13 c.852_855delCATA (n = 7), GJB2 c.235delC (n = 7), and PALB2 c.C2257T (n = 2) were the variants observed more than once across cancers." (PMID 33889545, 2021). "GJB2 gene product connexin 26 was suggested to promote cancer development by facilitating cell migration and invasion." (PMID 33348918, 2020). "GJB2 and SCN9A are implicated in monogenic diseases with emerging implications in cancer." (PMID 38177502, 2024). "The expression of cytoplasmic GJB2 protein was higher in cancer tissue than in adjacent tissues." (PMID 39162005, 2024). "Predicated on the anti‐neoplastic efficacy of GJB2, as indicated by the preceding experiments, the drugs that inhibit GJB2 activity could pave the way for a novel stratagem in cancer immunotherapy." (PMID 39162005, 2024). "The localization of GJB2 in HCC cancer cells is changed compared with normal liver tissue." (PMID 39162005, 2024). "Moreover, future prospective studies with larger sample sizes are needed to further validate the clinical value of GJB2 in pan-cancer." (PMID 37427102, 2023). "As a result, we hypothesized that GJB2 was not only a promising prognostic factor for multiple cancer types but also a potential target for immunotherapy." (PMID 37427102, 2023). "GJB2 plays an essential role in the growth and progression of several cancers." (PMID 37427102, 2023). "Next, we further evaluated the function of GJB2-positive CAFs in cancer tissues." (PMID 37648762, 2023). "However, it is important to acknowledge that the influence of GJB2 expression in cancer cells cannot be excluded." (PMID 37648762, 2023). "Therefore, in this study, we performed a comprehensive pan-cancer analysis to determine the potential role of GJB2 in prognostic prediction and cancer immunotherapy response." (PMID 37427102, 2023). "Finally, the study investigated the clinical significance of GJB2 signature score for GJB2-positive CAFs in cancer and found a correlation with poor prognosis." (PMID 37648762, 2023). "This also suggested that GJB2 was a promising anti-cancer drug target." (PMID 37427102, 2023). "Therefore, we investigated the clinical significance of GJB2-positive CAFs in cancer by measuring the GJB2 signature score in 8469 cancer tissues from The Cancer Genome Atlas." (PMID 37648762, 2023). "Interestingly, although GJB2-positive CAFs mainly signaled to cancer cells, the main source cells that actively signaled to GJB2-positive CAFs were blood vessel endothelial cells." (PMID 37648762, 2023). "Furthermore, GJB2 is a potential prognostic biomarker and a promising therapeutic target in multiple types of cancers." (PMID 37427102, 2023). "Furthermore, in most cancer types, GJB2 expression levels showed positive correlation with the ESTIMATE scores." (PMID 37427102, 2023). "Therefore, we first comprehensively analyzed the GJB2 gene expression in the pan- cancer datasets from various databases." (PMID 37427102, 2023). "One mechanism by which GJB2 exerts its cancer-specific relevant effects could be traced back to the changes in this pathway." (PMID 37188183, 2023).
cancer (continued). "Hence, we studied the association between GJB2 expression levels and the status of TMB, MSI, neoantigens, and ICP in human cancers to determine the potential of GJB2 as a biomarker of immunotherapy response." (PMID 37427102, 2023). "This suggested that GJB2 was a potential therapeutic target for future anti-cancer immunotherapy." (PMID 37427102, 2023). "Furthermore, GJB2 expression levels showed positive correlation with the ESTIMATE scores in several cancer types." (PMID 37427102, 2023). "The cancer patients were classified into high and low expression groups based on the GJB2 expression levels and the survival outcomes were determined based on the GJB2 expression levels in various tumors to determine the prognostic value of GJB2." (PMID 37427102, 2023). "In most cancer types, patients with a high GJB2 signature score tended to have poor prognosis." (PMID 37648762, 2023). "Early reports have been revealed GJB2 is involved in the progression of cancers." (PMID 35196203, 2022). "GJB2 has been shown to be correlated with the prognosis of cancer patients." (PMID 35936685, 2022). "Stenotrophomonas, an opportunistic pathogen with increased colonization/infection in cancer patients, exhibited extensive positive associations with the hypermethylation of genes, including multiple TSGs in CRC, such as ESR1, RASSF5, DIRAS1, CADM1, ST5, GJB2, FAM172A, and HIVEP3." (PMID 38840170, 2024). "This may be related to the increased expression of GJB2 and the degree of differentiation of different cancers, indicating that GJB2 can be used as a potential prognostic marker and therapeutic target for the poor survival of cancer patients." (PMID 38172427, 2024). "Therefore, we hypothesized that patients with high GJB2 expression levels as well as high TMB and MSI may show better prognosis after immunotherapy in those cancers where the GJB2 expression levels demonstrate positive correlation with TMB and MSI." (PMID 37427102, 2023). "Furthermore, GJB2 expression levels showed significant positive or negative association with the survival outcomes in various cancers." (PMID 37427102, 2023). "Moreover, GJB2 was poorly expressed in normal tissues, indicating that its expression is dependent on interaction with other cells, including vascular endothelial cells and cancer cells." (PMID 37648762, 2023). "We also detected the expression of GJB2 protein in the cell membrane, cytoplasm, and nucleus of HCC cancer cells from mouse organoids and normal liver cells." (PMID 39162005, 2024). "The second cluster, including one CPG (GJB2), and 21 OMIM genes, is characterized by high TAU score and LOEUF scores but relatively low two-hit preferences in a pan-cancer analysis compared to single cancer types." (PMID 38143269, 2023). "The heat map shows positive correlation between GJB2 and the five genes (GJB6, KRT6A, KRT6B, KRT14, and IVL) in pan-cancer." (PMID 37427102, 2023). "Among these genes, only expression levels of GJB2, S100A2, SPOCK2 and TGM1 were significantly upregulated in cancer samples and their high expression indicated poor prognosis (OS or RFS)." (PMID 31794425, 2019). "Overall, patients with a high GJB2-positive signature score showed poor prognosis, and this is a prognostic factor independent of cancer stage, age, and sex." (PMID 37648762, 2023). "After analyzing the frequencies of P/LP variants on GJB2 and SLC25A13 genes, we suggest that these two genes may not be cancer‐related genes and need be re‐evaluated." (PMID 35861108, 2023). "Furthermore, the relationship between GJB2 expression and various clinicopathological parameters in the pan-cancer datasets has not been studied." (PMID 37427102, 2023).
cancer (continued). "GJB2 may also be a potential prognostic factor for KIRC, as shown by pan-cancer analysis." (PMID 36016609, 2022). "However, recent studies of clinical samples suggested a different role of connexins in that expression levels and membrane localization of connexins, including Connexin 43 (Cx43, GJA1) and Connexin 26 (Cx26, GJB2), were found to be enhanced in metastatic lesions of cancer patients." (PMID 30642339, 2019). "Moreover, pan-cancer analysis of the essential role of GJB2 has not been investigated." (PMID 37427102, 2023). "RARRES1, NRIP1, GJB2 and others showed a negative correlation with MAPK12 and might be cancer suppressor genes in DLBCL." (PMID 38773060, 2024). "The relationship between GJB2, CTRL and cancer progression was not reported." (PMID 30410422, 2018). "Therefore, we suggest that GJB2 and SLC25A13 may not be cancer‐related genes according to the results of statistic test." (PMID 35861108, 2023).